DNMT1 (DNA methyltransferase 1)
Diseases named in the same sentence as DNMT1 in open-access papers (continued):
Sharing a sentence is not in itself a finding about the gene and the disease.
myeloma (21 papers, 2014 to 2025). "Similarly, it has been elucidated that DNMT1 overexpression causes methylation of HTR2A promoter in myeloma cells and that miR-140-3p overexpression is linked to decline of DNMT1 expression in WL-2 cells." (PMID 35710537, 2022). "In this regard, we hypothesized that the dual inhibition of DNMT1 and G9a could reactivate hypermethylated and silenced genes of MSCs from MM patients preserving their osteogenic potential and therefore preventing myeloma-associated bone loss." (PMID 33462210, 2021). "In the current study, RNA interference was employed to knock down DNMT1 expression in human MM cells to investigate the association between DNMT1 expression and the proliferative activity, tumor suppressor gene expression and gene methylation levels of myeloma cells." (PMID 25289094, 2014). "In particular, HDAC3 has been reported to regulate c-Myc protein levels, thereby HDAC3 inhibition increased acetylation of c-Myc as well as DNMT1 in myeloma cells, leading to degradation of DNMT1 and inhibition of myeloma cell growth." (PMID 38284882, 2024). "The efficacy of this combination treatment was confirmed in vivo using a murine xenograft MM model and the rationale for combined treatment using HDAC3 and DNMT1 inhibitors, as a novel strategy for myeloma therapy, was suggested." (PMID 30987296, 2019). "Combined HDAC3 inhibitor and AZA, a DNMT1 inhibitor, was found to synergistically downregulate DNMT1, resulting in the growth inhibition and apoptosis of MM cell lines and myeloma patient-derived cells." (PMID 30987296, 2019). "In the present study, it was found that DNMT1 expression was significantly downregulated at both the mRNA and protein level in RPMI-8226 myeloma cells following treatment with DNMT1 siRNA." (PMID 25289094, 2014). "In the present study, silencing of DNMT1 with siRNA was performed in RPMI-8226 human multiple myeloma (MM) cells, and the impact on gene methylation status and proliferation of the cells was analyzed." (PMID 25289094, 2014). "UA might interact with USP7 in RPMI8226 human myeloma cells and could inhibit myeloma cell proliferation (IC50 = 6.56 μmol/L), accompanied by reductions in USP7 substrates such as MDM2, UHRF1, and DNMT1 related to the inhibition of USP7." (PMID 34835969, 2021). "The simultaneous inhibition of HDAC3 and DNMT1 using the BG45 and DNMT1 inhibitors 5-azacytidine (AZA), respectively, has been found to induce synergistic DNMT1 downregulation, growth inhibition and apoptosis in multiple myeloma (MM) cell lines and MM patients." (PMID 38490978, 2024).
endometrial cancer (20 papers, 2010 to 2025). Primary or metastatic malignant neoplasm involving the endometrium (mucous membrane that lines the endometrial cavity). "Loss of exosomal miR-148b from CAFs also promotes endometrial cancer cell invasion and cancer metastasis via binding to DNA methyltransferase 1 (DNMT1), as shown in a recent study." (PMID 33869017, 2021). "CAFs promoted metastasis to lungs in vivo; Low levels of miR-148b within CAF-derived exosomes promote endometrial cancer cell migration and invasion; loss of miR-148 results in de-repression of its target DNMT1." (PMID 32957712, 2020). "miR-148b functions as a tumor suppressor in endometrial carcinoma cells by directly binding and suppressing DNA methyltransferase 1 (DNMT1) and its effects of inducing EMT, thereby suppressing endometrial cancer metastasis." (PMID 37046676, 2023). "In another female tumor, endometrial cancer, PIWIL1 caused the silence of PTEN expression through DNMT1-mediated hypermethylation." (PMID 35637965, 2022). "Notably, DNMT1 silencing has been shown to increase Bax expression while decreasing Bcl‐2 and CCND1/2 in AN3CA cells, suggesting the potential of DNMT1 in endometrial carcinoma (EC) therapy." (PMID 40387409, 2025). "Endometrial cancer cell CAF exosomes have significantly lower miR-148b levels than normal fibroblasts and promote endometrial cancer cell invasion and metastasis, as they have lost the suppressive effects of the exosomal transfer on mir-148b on DNMT1-mediated EMT." (PMID 37046676, 2023). "Therefore, the PIWIL1/DNMT1/PTEN signaling pathway may play a significant role in the progression of type I endometrial cancer." (PMID 35637965, 2022). "For instance, exosomal miR-148b was transferred from CAFs to endometrial cancer cells and then processed EMT of cancer cells by directly targeting DNMT1." (PMID 30646925, 2019). "We observed that L1CAM positive endometrial carcinoma (EC) cell lines HEC1B and SPAC1L lost L1CAM protein and mRNA by treatment with demethylating agents or knock-down of the DNA-methyltransferase-1 (DNMT1)." (PMID 24497324, 2014). "Overexpression of DNA methyltransferase 1 microRNA was mainly observed in endometrial carcinomas rather than in normal tissues or EINs." (PMID 37671063, 2023). "Additionally, cancer-associated fibroblasts (CAFs) can secrete exosomes lacking miR-148b that are transferred to endometrial cancer cells (ECCs) and modulate EMT by relieving the suppression of DNA (cytosine-5)-methyltransferase 1 (DNMT1)." (PMID 31467934, 2019).
renal fibrosis (20 papers, 2015 to 2025). A final common manifestation of a wide variety of chronic kidney diseases characterized by glomerulosclerosis and tubulointerstitial fibrosis. "This study found hyper-methylation of RASAL1 by the methyltransferase Dnmt1 and that gene reduction of Dnmt1 in a mouse model was associated with reduced renal fibrosis." (PMID 27190345, 2017). "Although increasing evidence indicates UHRF1 assists DNMT1 in maintaining DNA methylation, current understanding of its pathological function in renal fibrosis is unclear." (PMID 40490444, 2025). "DNMT1-mediated DNA maintenance methylation plays an important role in the progression of renal fibrosis." (PMID 40490444, 2025). "YB-1 is a yet unreported essential part of the DNMT1–Klotho-dependent epigenetic cascade promoting renal fibrosis." (PMID 38474331, 2024). "DNMT1 regulates MEG3 expression by altering the methylation level of the MEG3 promoter in TGFβ1-induced renal fibrosis, thereby affecting the development of renal fibrosis." (PMID 36869378, 2023). "In the context of renal fibrosis, hydralazine was observed to downregulate mRNA expression of DNMT1 and induce expression of DNMT3a and Tet3." (PMID 33735324, 2021). "Inhibition of DNMT1 expression or activity contributes to improvement of renal fibrosis." (PMID 40490444, 2025). "Additionally, it was previously demonstrated that miR-185 inhibitor significantly up-regulated DNMT1 expression in HK2 cell line, and by modulating DNMT1 thereby regulating MEG3 expression in TGF-β1-induced renal fibrosis." (PMID 38413914, 2024). "In summary, our studies suggest that Hydralazine ameliorates experimental renal fibrosis through inducing de-methylation of aberrantly methylated Rasal1 (and additional genes as well) by Dnmt1 inhibition and by inducing the endogenous Tet3/Tdg de-methylation pathway." (PMID 25717475, 2015). "In the progression of renal fibrosis, ROS can promote hypermethylation of the NDRG2 promoter, which is consistent with findings in diabetic retinopathy, where inhibiting DNMT1 was shown to reduce ROS levels." (PMID 40553255, 2025). "Consistent with our study, DNMT1 has been reported as a unique DNMT subtype that mediates hypermethylation of the RasalI promoter, thereby leading to persistent renal fibrosis." (PMID 35765066, 2022). "As a critical cooperator in DNA methyltransferase 1 (DNMT1)-mediated maintenance of DNA methylation, the role of ubiquitin-like containing PHD and RING finger domains 1 (UHRF1) in renal fibrosis remains unknown." (PMID 40490444, 2025). "Interestingly, in renal fibrosis, it has been reported that long term TGF-β1 stimulation induced DNA methylation, but DNMT1 was found to be related to this change." (PMID 31603936, 2019). "DNMT1 could represses Krüppel-like factor 4(KLF4) through bind to its promoter regions and contributes to EMT in renal fibrosis." (PMID 29221147, 2017).
Insulin resistance (19 papers, 2015 to 2026). Increased resistance towards insulin, that is, diminished effectiveness of insulin in reducing blood glucose levels. "Genetic or chemical targeting hepatic DNMT1 shows significant benefits against insulin resistance associated metabolic disorders." (PMID 34141522, 2021). "Consistent with this, elevated DNMT1 expression has been observed in adipocytes of obese humans and mice, in association with insulin resistance through adiponectin promoter hypermethylation and decreased adiponectin mRNA expression." (PMID 34485290, 2021). "In conclusion, our findings demonstrated that hesperidin improved oxidative stress, mitochondrial dysfunction and insulin resistance by inhibiting DNMT1-mediated miR-149 silencing." (PMID 33926520, 2021). "Our findings demonstrated that hesperidin treatment ameliorated HG-induced insulin resistance by reducing oxidative stress and mitochondrial dysfunction partly by suppressing DNMT1-mediated miR-149 silencing." (PMID 33926520, 2021). "Hepatic knockdown of ND6 or overexpression of Dnmt1 similarly impairs mitochondrial function and induces systemic insulin resistance both in vivo and in vitro." (PMID 34141522, 2021). "Among the known DNA methyltransferases, DNMT1 promotes insulin resistance by mediating DNA methylation in HFD-induced obese mice." (PMID 31387996, 2019). "Thus, we propose that insulin resistance may regulate DNMT1 activity and DNA methylation in the D-loop region through NAD+-SIRT1, and this mechanism should be further explored in future studies." (PMID 26110043, 2015). "When compared with untreated cells, we also found that DEX or TNF-α treatment of C2C12 cells induced insulin resistance, as demonstrated by the inactivation of mTOR, and reduced Dnmt1 expression and enhanced expression of miR-193b." (PMID 34913989, 2022).
nasopharyngeal carcinoma (19 papers, 2009 to 2025). A carcinoma arising from the nasopharyngeal epithelium. "LMP1 up-regulates DNMT1, DNMT3A, and DNMT3B in EBV-associated nasopharyngeal carcinoma (latency II)." (PMID 32841292, 2020). "One report demonstrated that Epstein-Barr virus (EBV)-encoded latent membrane protein 1 (LMP1)-mediated activation and expression of DNMT1 involved in activation of JNK/MAPK in nasopharyngeal carcinoma cells." (PMID 26362062, 2015). "explored the involvement of the DNMT1/miR‐142‐3p/ZEB2 axis in nasopharyngeal carcinoma (NPC)." (PMID 40387409, 2025). "Furthermore, miR-142-3p has been shown to be epigenetically inhibited by EZH2-recruited DNMT1, suppressing the metastasis of nasopharyngeal carcinoma." (PMID 38890707, 2024). "Studies on nasopharyngeal carcinoma (NPC) showed LMP1 induced DNMT-1 protein and RNA expression NP69 (stably expressed LMP1), in addition to siRNA targeting of JNK, c-Jun and TRADD, LMP1-YYD domain and LMP1 observed reduced DNMT-1 expression by 20%, 40%, 60% and 50%." (PMID 33670008, 2021). "Moreover, IL-8 was shown to increase the methylation of CDH1 gene promoter in nasopharyngeal carcinoma cells by upregulating DNMT1 via the AKT pathway." (PMID 32678024, 2020). "Although only one gene promoter was analyzed, it cannot be excluded that p-c-Jun and consequent DNMT1 regulation in nasopharyngeal carcinoma might affect methylation of a larger set of genes." (PMID 28036297, 2017). "In nasopharyngeal carcinoma cells (NPCs), β-elemene inhibits DNA damage repair and NPC cell growth via inactivation of Stat3 and reduces DNMT1 and EZH2 expression." (PMID 37121970, 2023). "For instance, in EBV-driven nasopharyngeal carcinoma (NPC) cell lines, LMP1 activates the c-jun N-terminal kinase (JNK) pathway, thereby leading to DNMT1 upregulation." (PMID 37298494, 2023). "In nasopharyngeal carcinoma, miR-142-3p was downregulated by DNA methylation due to EZH2’s recruitment of DNMT1 which occupied the upstream region of the miR-142 and determined ZEB2 activation, leading to EMT and metastasis." (PMID 33014831, 2020). "In nasopharyngeal carcinoma (NPC) cells, LMP1 activates DNMT1 through the activation of c-Jun NH2-terminal kinase (JNK)-activator protein-1 (AP-1) signaling." (PMID 21416003, 2009).
Sepsis (19 papers, 2016 to 2025). Sepsis is defined as life-threatening organ dysfunction caused by a dysregulated host response to infection. "Currently, drugs targeting DNMT1 inhibitors face challenges related to specificity when applied to sepsis treatment." (PMID 40766066, 2025). "DNMT1-mediated inhibition of Bcl-2 expression promoted inflammation and apoptosis, contributing to myocardial injury in this LPS-induced sepsis model." (PMID 37947606, 2023). "In this study, we investigated the role of lncRNA SNHG1 in sepsis‐induced myocardial injury and illustrated that lncRNA SNHG1 promoted sepsis‐induced myocardial injury by regulating the DNMT1/Bcl‐2 axis." (PMID 35678255, 2022). "Bioinformatics analysis showed upregulated DNMT1 expression and suggested upregulated NF-κB signalling pathway-related genes in patients with sepsis." (PMID 35335337, 2022). "Intriguingly, accumulating evidence has unfolded the participation of DNMT1 in sepsis and myocardial injury." (PMID 35678255, 2022). "This study aims to investigate the molecular mechanism of long noncoding RNA (lncRNA) small nucleolar RNA host gene 1 (SNHG1)‐mediated DNA methyltransferase 1/B‐cell lymphoma‐2 (DNMT1/Bcl‐2) axis in sepsis‐induced myocardial injury." (PMID 35678255, 2022). "Humans with sepsis upregulate DNMT1, DNMT3a and DNMT3b, resulting in global DNA methylation differences, 82.6% of which are suppressive hypermethylated marks." (PMID 34163486, 2021). "Upregulated DNMT1, DNMT3a and DNMT3b, resulting in global DNA hypermethylation methylation in sepsis." (PMID 34163486, 2021). "The levels of all 3 DNMTs in CLP-induced sepsis mice tended to increase compared to those of the sham group, but only DNMT1 showed a significant elevation." (PMID 32714333, 2020). "Overall, lncRNA SNHG1 regulated the DNMT1/Bcl‐2 axis to promote sepsis‐induced myocardial injury." (PMID 35678255, 2022). "As previously reported, DNMT1 resulted in hypermethylation of miR‐145 promoter to downregulate miR‐145 expression, which promoted sepsis induced by LPS and shortened the overall survival of mice with sepsis." (PMID 35678255, 2022). "Interestingly many reports showed an increase in the expression of DNA methylating enzymes such as DNA methyltransferase 1 (DNMT1) in septic patients and in endotoxin cell culture models of sepsis." (PMID 33066217, 2020). "In our work, we could verify that PBMCs in an endotoxemia model of sepsis showed an increased cellular expression of the methyltransferase DNMT1." (PMID 33066217, 2020). "Therefore, we made a hypothesis in the present study that lncRNA SNHG1 may orchestrate the DNMT1/Bcl‐2 axis to affect the sepsis‐induced myocardial injury." (PMID 35678255, 2022). "We thus examined the expression levels of DNMT1 and DNMT3A and found that both genes were significantly upregulated within the IECs of CS-injected sepsis mice compared to those of sham mice." (PMID 36899862, 2023).
Sepsis (continued). "This can be achieved by the enzymatic activity of DNMT1 and DNMT3A in DNA methylations and/or by the posttranscriptional regulation of the miRNAs (such as miR-149-5p, miR-466q, miR-495, and miR-511-3p) upregulated in the sepsis IECs." (PMID 36899862, 2023). "GO analysis of the DE RBPs in sepsis identified terms that were mostly enriched in the immune/inflammatory response; we identified significant differences in 8 down-regulated RBPs in sepsis, including DDX24, CBFA2T2, NOP, ILF3, DNMT1, FTO, PPRC1, NOLC1." (PMID 37749550, 2023). "Thus, the expression levels of the eight RBPs (DDX24, CBFA2T2, NOP14, ILF3, DNMT1, FTO, PPRC1, and NOLC1) were altered in the patients with sepsis might potentially be useful as novel biomarkers as well as targets to facilitate the diagnosis and management of sepsis." (PMID 37749550, 2023).